UCN3 (urocortin 3)
Diseases named in the same sentence as UCN3 in open-access papers (continued):
Sharing a sentence is not in itself a finding about the gene and the disease.
Obesity (4 papers, 2006 to 2022). Accumulation of substantial excess body fat. "We and others have also reported impaired UCN3 expression associated with obesity, type 2 diabetes (T2D), and polycystic ovary syndrome." (PMID 35276788, 2022). "In a cross-species association study, UCN3 was proposed to be linked to obesity due to its location on human chromosome 10p15.1 where quantitative trait loci for obesity have been reported." (PMID 31781037, 2019). "Our results also show that moderate physical exercise differentially modulates UCN3 levels in the body and provides further evidence for the effect of physical exercise in mitigating metabolic stress linked with obesity and insulin resistance." (PMID 31781037, 2019). "The promoter polymorphisms of the bovine UCN3 gene alter 12 potential transcription regulatory binding sites, some of which are associated with obesity-related conditions." (PMID 17183713, 2006). "However, the distribution of CRFR2 and UCN3 in adipose tissue and the mechanisms underlying their role in obesity and adipose tissue-related insulin resistance remain unclear." (PMID 31781037, 2019). "Of note, the UCN3 plasma levels were significantly increased in overweight children but blunted in those with obesity." (PMID 35276788, 2022). "We found that UCN3 is associated with markers of glucose metabolism in humans and that there is differential dysregulation of UCN3 levels with obesity and T2D in plasma and SAT." (PMID 31781037, 2019). "Our findings of impaired UCN3 levels in obesity and T2D with opposite pattern between plasma and SAT indicate the complexity of mechanisms under these conditions." (PMID 31781037, 2019). "To elucidate the role of UCN3 in obesity and T2D, we assessed UCN3 expression levels in SAT from representative individuals from the three groups." (PMID 31781037, 2019). "Moreover, because of the co-localization of UCN3 with quantitative trait loci for obesity, UCN3 and CRFR2 were suggested as targets for obesity treatment." (PMID 35276788, 2022). "Furthermore, impaired UCN3 expression is reported in various metabolic syndromes, such as type 2 diabetes (T2D), obesity, polycystic ovary syndrome (PCOS), and sleep apnea." (PMID 34341463, 2021). "Because UCN3 is located on human chromosome 10p15.1 where quantitative trait loci for obesity have been reported, our cross species study provides further evidence that it could be proposed as a potential target for developing antiobesity drugs." (PMID 17183713, 2006). "Interestingly, UCN3 and CRHR2 are proposed as potential anti-obesity targets owing to their co-location with quantitative trait loci for obesity on chromosome 10p15.116." (PMID 34341463, 2021). "Overall, significant negative correlations were observed for UCN1 expression and obesity markers (BMI, percentile, body fat percentage, and cholesterol), for UCN3 and TNFα and NGAL, as well as for CRH and TNFα, RBP4, ZAG, and circulating UCN2 levels (p < 0.05)." (PMID 35276788, 2022).
colon cancer (3 papers, 2013 to 2025). "Urocortin 3 (UCN3), a peptide hormone, is associated with cuproptosis and immunity in colon cancer." (PMID 40255484, 2025).
Insulin resistance (3 papers, 2014 to 2023). Increased resistance towards insulin, that is, diminished effectiveness of insulin in reducing blood glucose levels. "However, further studies are required to understand the cross talk between UCN3 levels and insulin resistance, and its role in adipose tissue, including the status of CRF receptors in SAT." (PMID 31781037, 2019). "Given the published effects that UCN2 and UCN3 have on insulin signaling, we began by investigating circulating UCN2 and UCN3 levels in established genetic models of insulin resistance." (PMID 37402735, 2023).
type 2 diabetes (3 papers, 2017 to 2022). "Recent studies suggested the presence of immature, Ucn3-negative and insulin-positive cells in the islets from donors with type 2 diabetes." (PMID 28939870, 2017). "This study investigated the effects of Type 2 diabetes (T2D) and increased body weight on the circulatory and subcutaneous adipose tissue (SAT) levels of UCN3 and assessed UCN3 modulation by a regular physical exercise." (PMID 31781037, 2019).
depression (2 papers, 2021 to 2023). "Based on the original, dualistic hypothesis, generalized anxiety disorder and major depression disorder could be treated by the inhibition of CRF1 with selective antagonists, such as antalarmin, or via the activation of CRF2 with selective agonists, such as Ucn2 or Ucn3." (PMID 37626714, 2023).
heart failure (2 papers, 2016 to 2020). Inability of the heart to pump blood at an adequate rate to meet tissue metabolic requirements. "Urocortin 2 produced similar responses to urocortin 3, although increases in cardiac index and heart rate were only significant in heart failure (P < 0.05) and healthy subjects (P < 0.001), respectively." (PMID 27275843, 2016). "We aimed to examine the local and systemic cardiovascular effects of urocortin 2 and urocortin 3 in healthy subjects and patients with heart failure." (PMID 27275843, 2016). "We conclude that these data provide further evidence suggesting urocortin 2 and urocortin 3 continue to hold promise for the treatment of heart failure." (PMID 27275843, 2016). "The increase in heart rate at the highest dose of urocortin 3 was less pronounced in patients with heart failure and this was likely due to concomitant β‐adrenoceptor blocker therapy." (PMID 27275843, 2016). "Otherwise urocortin 2 and urocortin 3 increased cardiac index and heart rate and reduced mean arterial pressure and peripheral vascular resistance index in both patients with heart failure and healthy subjects (P < 0.05 for all)." (PMID 27275843, 2016). "UCN2 and UCN3 are expressed in the heart and may have beneficial effects on cardiovascular pathophysiology, particularly heart failure (HF)." (PMID 31935997, 2020). "Over the infusion and washout period, urocortin 3 again caused a greater increase in cardiac output (P < 0.0001) than urocortin 2 in patients with heart failure but not in healthy subjects (P = 0.48)." (PMID 27275843, 2016). "Urocortin 2 and urocortin 3 may play a role in the pathophysiology of heart failure and are emerging therapeutic targets." (PMID 27275843, 2016). "However, we demonstrate that urocortin 2 and urocortin 3 evoked normal forearm arterial vasodilatory responses in our patients with heart failure." (PMID 27275843, 2016). "Heart failure patients (n = 9) and healthy subjects (n = 7) underwent non‐invasive impedance cardiography during incremental intravenous infusions of sodium nitroprusside (573–5730 pmol kg−1 min−1 ), urocortin 2 (36–360 pmol min−1 ), urocortin 3 (1.2–12 nmol min−1) and saline placebo." (PMID 27275843, 2016).
itch (2 papers, 2022 to 2024). "Here, using whole-cell patch-clamp recordings, we observed increased excitability in spinal Ucn3+ neurons under chronic itch conditions." (PMID 35782385, 2022). "The differences in the AP properties suggest an increased excitability of Ucn3+ neurons under chronic itch conditions." (PMID 35782385, 2022). "Our experimental recordings demonstrated that Ucn3+ mechanical itch transmission neurons in the dorsal spinal cord become more excitable under chronic itch conditions, while NPY+ inhibitory gating neurons in the dorsal spinal cord become less excitable." (PMID 35782385, 2022). "The majority of Ucn3+ neurons exhibited initial bursting firing in response to depolarizing current pulses in both the control and chronic itch groups." (PMID 35782385, 2022). "In this study, we first examined the excitability of Ucn3+ neurons under chronic itch conditions." (PMID 35782385, 2022). "Gentle touch applied to the skin can simultaneously activate both the neural circuitry involved in transmitting mechanical itch (e.g., TLR5+ LTMRs to Ucn3+/Tac2+ INs) and an inhibitory neural circuitry that effectively suppresses mechanical itch." (PMID 39602426, 2024). "Our models demonstrated that changes in Nav1.6 conductance are predominantly responsible for the changes in excitability of both Ucn3+ and NPY+ neurons during chronic itch pathogenesis." (PMID 35782385, 2022). "We observed several concurrent changes in the AP properties and ion channel expression levels of Ucn3+ and NPY+ neurons under chronic itch conditions." (PMID 35782385, 2022). "Our model populations are currently simulating the most excitable subset of our experimentally measured Ucn3+ and NPY+ neurons in both control and chronic itch groups." (PMID 35782385, 2022). "Our modeling results indicate that Nav1.6 may be the major component to alter excitability in both Ucn3+ and NPY+ neurons under chronic itch conditions." (PMID 35782385, 2022).
endometrial cancer (1 paper, 2017). Primary or metastatic malignant neoplasm involving the endometrium (mucous membrane that lines the endometrial cavity). "Further work is required to understand the mechanisms through which UCN1 suppresses endometrial cancer cell migration, and to characterize the role of UCN2, UCN3, and the CRF‐BP in endometrial cancer." (PMID 28109061, 2017).
endometriosis (1 paper, 2019). The growth of functional endometrial tissue in anatomic sites outside the uterine body. "Both UCN2 and UCN3 expression levels were significantlylower in women with endometriosis when comparedwith healthy women." (PMID 30644237, 2019). "In women suffering from endometriosis, theexpression of UCN, UCN2 and UCN3 transcripts wasthe same in the secretory and the proliferative phases,whereas in healthy women UCN levels differed betweenthe two phases." (PMID 30644237, 2019).
Hypoglycemia (1 paper, 2025). A decreased concentration of glucose in the blood. "Ucn3 neurons in the MeA process information related to social behavior and social memory, and are activated by stress−related signals such as hypoglycemia." (PMID 39859453, 2025).
hypopharyngeal cancer (1 paper, 2025). Carcinoma, predominantly squamous cell, arising from the epithelial cells of the hypopharynx. "For hypopharyngeal cancer, GHRH, UCN3, LCE2B, DDC, and PCDHGC5 were upregulated." (PMID 40255484, 2025).
obstructive sleep apnea (1 paper, 2019). "Furthermore, UCN3 is present in urine, and levels are significantly increased in patients with obstructive sleep apnea." (PMID 31781037, 2019).
preeclampsia (1 paper, 2024). Preeclampsia is a hypertensive disorder of pregnancy that is characterized by new-onset hypertension with proteinuria presenting after 20 weeks of gestation, and depending on mild or severe forms may initially present with severe headache, visual disturbances, and hyperreflexia. "In the hypoxic-ischemic environment of preeclampsia, a novel member of the CRH peptide family significantly increases Ucn2 and Ucn3, further promoting the response to oxidative stress in the placenta." (PMID 38894741, 2024).
metabolic disease (2 papers, 2019 to 2021). A congenital disorder (due to inherited enzyme abnormality) or acquired (due to failure of a metabolically important organ) disorder resulting from an abnormal metabolic process. "Hence, a better understanding of the molecular mechanisms that regulate UCN3 expression and action is expected to provide critical insight into its role in the pathophysiology of various metabolic disorders." (PMID 34341463, 2021).
tumor (1 paper, 2013). "Statistical analysis revealed a significant increase of CRF2α and Ucn3 mRNA expression in tumors compared to normal tissues according to the tumor grade." (PMID 24260200, 2013).
UCN3 also shares sentences with these, for which no sentence is quoted: cancer (1 paper); cardiovascular disease (1); chronic heart failure (1); colon adenocarcinoma (1); generalized anxiety disorder (1); hearing loss (1); Hyperinsulinemia (1); hypothyroidism (1); Infertility (1); melanoma (1); polycystic ovary syndrome (1).